TRAF3 (TNF receptor associated factor 3)
Description:
Cytoplasmic E3 ubiquitin ligase that regulates various signaling pathways, such as the NF-kappa-B, mitogen-activated protein kinase (MAPK) and interferon regulatory factor (IRF) pathways, and thus controls a lot of biological processes in both immune and non-immune cell types. In TLR and RLR signaling pathways, acts as an E3 ubiquitin ligase promoting the synthesis of 'Lys-63'-linked polyubiquitin chains on several substrates such as ASC that lead to the activation of the type I interferon response or the inflammasome. Following the activation of certain TLRs such as TLR4, acts as a negative NF-kappa-B regulator, possibly to avoid unregulated inflammatory response, and its degradation via 'Lys-48'-linked polyubiquitination is required for MAPK activation and production of inflammatory cytokines. Alternatively, when TLR4 orchestrates bacterial expulsion, TRAF3 undergoes 'Lys-33'-linked polyubiquitination and subsequently binds to RALGDS, mobilizing the exocyst complex to rapidly expel intracellular bacteria back for clearance. Also acts as a constitutive negative regulator of the alternative NF-kappa-B pathway, which controls B-cell survival and lymphoid organ development. Required for normal antibody isotype switching from IgM to IgG. Plays a role T-cell dependent immune responses. Down-regulates proteolytic processing of NFKB2, and thereby inhibits non-canonical activation of NF-kappa-B. Promotes ubiquitination and proteasomal degradation of MAP3K14.
Synonyms: CRAF1; CD40BP; LAP1; CAP-1; RNF118; IIAE5; IMD132A; IMD132B
Tractability: PROTAC: UniProt records ubiquitination sites on it; ubiquitination databases record sites on it.
Gene: Protein-coding gene on chromosome 14 (102,777,326 to 102,911,500, forward strand). Ensembl gene ENSG00000131323.
Subcellular location: Cytoplasm; Endosome; Mitochondrion
Pathways (Reactome):
Immune System: Activation of IRF3, IRF7 mediated by TBK1, IKKε (IKBKE); Negative regulators of DDX58/IFIH1 signaling; Regulation of TBK1, IKKε (IKBKE)-mediated activation of IRF3, IRF7; Regulation of TBK1, IKKε-mediated activation of IRF3, IRF7 upon TLR3 ligation; TICAM1-dependent activation of IRF3/IRF7; TNF receptor superfamily (TNFSF) members mediating non-canonical NF-kB pathway; TNFR2 non-canonical NF-kB pathway; TRAF3-dependent IRF activation pathway
Disease: SARS-CoV-1 activates/modulates innate immune responses; SARS-CoV-2 activates/modulates innate and adaptive immune responses; TRAF3 deficiency - HSE
Metabolism of proteins: Ovarian tumor domain proteases
Gene Ontology:
Molecular function: identical protein binding; protein binding; protein phosphatase binding; thioesterase binding; tumor necrosis factor receptor binding; ubiquitin protein ligase activity; ubiquitin protein ligase binding; ubiquitin-protein transferase activity; signaling adaptor activity; protein kinase binding; zinc ion binding
Biological process: positive regulation of type I interferon production; regulation of proteolysis; toll-like receptor 4 signaling pathway; toll-like receptor signaling pathway; tumor necrosis factor-mediated signaling pathway; apoptotic process; cell surface receptor signaling pathway; defense response to virus; regulation of canonical NF-kappaB signal transduction; regulation of cytokine production; regulation of defense response to virus; regulation of interferon-beta production; signal transduction; TRIF-dependent toll-like receptor signaling pathway; type I interferon-mediated signaling pathway; innate immune response; regulation of apoptotic process; regulation of type I interferon production; Toll signaling pathway
Cellular component: cytoplasm; endosome; endosome membrane; mitochondrion; CD40 receptor complex; cytoplasmic side of plasma membrane; cytosol; serine/threonine protein kinase complex; ubiquitin ligase complex; membrane
Genetic constraint (gnomAD): Loss-of-function variants: 13 observed, 64.35 expected, observed/expected ratio (o/e) 0.2, 90% interval 0.13 to 0.32. The upper end of that interval is the gene's LOEUF score, 0.32, which puts it in group 1 of 6, group 1 being the genes least tolerant of losing a copy. Missense variants: 440 observed, 777.37 expected, observed/expected ratio (o/e) 0.57, 90% interval 0.52 to 0.61. Synonymous variants: 269 observed, 298.66 expected, observed/expected ratio (o/e) 0.9, 90% interval 0.81 to 1.
Gene-disease validity (ClinGen):
ClinGen rates the evidence that TRAF3 causes each of these diseases.
TRAF3 haploinsufficiency (autosomal dominant): Moderate. Any Mendelian disease in which the cause of the disease is a mutation in the TRAF3 gene.
Homologues: Orthologues: chimpanzee TRAF3 (99% identical), macaque TRAF3 (99% identical), rabbit TRAF3 (97% identical), dog TRAF3 (96% identical), mouse Traf3 (96% identical), guinea pig TRAF3 (95% identical), pig TRAF3 (95% identical), rat Traf3 (95% identical), tropical clawed frog traf3 (78% identical), Caenorhabditis elegans trf-1 (23% identical), Caenorhabditis elegans trf-2 (14% identical). Paralogues in human: TRAF5 (41% identical), TRAF2 (29% identical), TRAF4 (25% identical), TRAF1 (24% identical), TRAF6 (23% identical).
Diseases named in the same sentence as TRAF3 in open-access papers:
TRAF3 is named in the same sentence as 168 diseases in open-access papers, as found by Europe PMC text mining. Sharing a sentence is not in itself a finding about the gene and the disease. The quoted sentences say what the papers report.
viral infection (68 papers, 2009 to 2026). "During viral infection, K63-linked polyubiquitination of TRAF3 recruits TBK1-IKKε, and IRF3 is then activated to trigger type I IFN production." (PMID 36056146, 2022). "We also note deficiencies in TRAF3 protein expression during viral infection in the single and double knockouts." (PMID 35085371, 2022). "Upon virus infection, K63-linked polyubiquitination of TRAF3 leads to the recruitment of TBK1 and the subsequent activation of IRF3 (54, –, 56)." (PMID 33975961, 2021). "We sought to determine the mechanism underlying the recruitment of the ER-to-Golgi resident TRAF3 to membrane-bound MAVS for the formation of functional signalling complex upon viral infection." (PMID 33411856, 2021). "During viral infection, K63-linked polyubiquitination of TRAF3 leads to the recruitment of TBK1-IKKε and subsequent activation of IRF3." (PMID 32562145, 2020). "Unlike the downregulation of Triad3A and TRAF3 in LPS‐treated macrophages, studies have shown that Triad3A negatively regulates TRAF3 through Lys48‐linked ubiquitination, knock‐down of Triad3A increased endogenous TRAF3 expression in A549 cells following virus infection." (PMID 37506157, 2023). "In addition, USP25 is upregulated after viral infection and participates in the body’s antiviral response by mediating the stabilization of tumor necrosis factor (TNF) receptor associated factor 3 (TRAF3) and TRAF6." (PMID 35096833, 2021). "We found that endogenous β-arrestin 2 could be associated with TBK1 and TRAF3 during virus infection." (PMID 33243993, 2020). "HSCARG also interacted with Ikappa-B kinase epsilon (IKKε) after viral infection and impaired the association between TRAF3 and IKKε, which further decreased the phosphorylation of IKKε and interferon response factor 3 (IRF3), thus suppressed the dimerization and nuclear translocation of IRF3." (PMID 24763515, 2014). "A similar scenario is proposed here where, in response to viral infection, the association of TRAF3 with complexes containing p115 and Sec16A at the ER-to-Golgi vesicular pathway may play an important role in positioning TRAF3 with MAVS." (PMID 22792062, 2012). "Stimulation by bacterial or viral infection may promote the activation of nuclear factor kappa-light-chain-enhancer of activated B cells (NF-κB) and tumor necrosis factor receptor-associated factor 3 (TRAF3) signaling pathways." (PMID 31731423, 2019). "Given that TRAF3-deficient mice die in the neonatal period, there lack definitive experimental data on the physiological functions of TRAF3 with respect to viral infection." (PMID 40552831, 2025). "Early studies reported that TRAF3 activates TBK1 upon virus infection and that TBK1 and IRF3 then form a complex." (PMID 40234418, 2025). "As a pivotal member of the RLR pathway, TRAF3 is essential for activating the MAVS/TBK-1/IRF3 signaling pathway in response to viral infection." (PMID 39058724, 2024). "Lastly, TRAF3 has been shown to be a critical component in the activation of IRF3 during the innate immune response to viral infections." (PMID 38589899, 2024). "In the case of viral infection, Lgals3bp forms complex with Traf6 or Traf3, and subsequently recruits TAK1 and TBK1, which then signal the translocation of the transcription factors NF-κB, IRF3, and IRF7 from the cytoplasm to the nucleus." (PMID 38279161, 2024). "The interaction of MAVS with TRAF3/6 plays a crucial role in various viral infection mechanisms by activating the IRF3, IRF7, and NF-kB pathways." (PMID 38995016, 2024). "This tendency of Triad3A and TRAF3 is a discrepancy with Nakhaei's findings that Triad3A negatively modulates the RIG‐I‐like receptor signaling by targeting TRAF3 for proteasomal degradation after virus infection." (PMID 37506157, 2023). "TRAF3IP3 binds to MAVS and facilitates its recruitment of downstream TRAF3 during viral infection, thereby promoting antiviral response." (PMID 37563140, 2023).
viral infection (continued). "Following viral infection, both TRAF3 and TRAF2 are recruited to the mitochondrial antiviral signaling complexes by MAVS, while in response to ER stress, TRAF2 is translocated to ER via interacting with the ER stress sensor IRE1α." (PMID 36776285, 2023). "Ubiquitination and deubiquitination of TRAF3 are critical to regulating interferon production and resisting viral infection." (PMID 36845015, 2023). "With the virus infection, the expression level of influenza PA mRNA gradually increased, but the expression of TRAF3 mRNA gradually decreased." (PMID 35573779, 2022). "Based on these findings, we will explore the functional characterization of the three domains of TRAF3 in response to virus infection in our future work." (PMID 35573779, 2022). "It is reported that the ectopic expression of either NS1 or NS2 reduces the protein level of TRAF3 in A549 cells, while only infection with NS1-deficient RSV, but not NS2-deficient virus increases the levels of TRAF3 compared to WT virus infection." (PMID 35308390, 2022). "Among them, TRAF3 is an important effector of innate immunity against viral infections by inducing antiviral response." (PMID 35573779, 2022). "TRAF3IP3 is a critical regulator for the downstream RIG-I/MDA-5 signaling pathway, and it accumulates on mitochondria in response to viral infection, driving TRAF3 to MAVS for TBK1-IRF3 activation." (PMID 35885892, 2022). "Together our work uncovers a novel mechanism of IAV NS1-mediated immune evasion to promote viral infection through targeting the RNA sensing-TRAF3-type I IFN axis." (PMID 34610835, 2021). "Interaction between endogenous TRAF3 and Nedd4l was also detectable in macrophages following virus infection." (PMID 33608556, 2021). "More TRAF3 protein was immunoprecipitated by the gradually increasing levels of TRIM35 expression across the infection course, indicating TRIM35 interacted with TRAF3 in vivo during natural viral infection." (PMID 32562145, 2020). "PINK1 positively regulates the antiviral immune response through enhanced association with TRAF3 and IRF3 upon virus infection, which promotes IRF3 phosphorylation and results in increased IFN-β and IL-6 transcription." (PMID 31139191, 2019). "Our results showed that PINK1 promoted TRAF3 expression upon viral infection, likely due to PINK1-mediated Parkin degradation and repressed Parkin-mediated TRAF3 K48-linked ubiquitination, leading to decreased TRAF3 degradation." (PMID 31139191, 2019). "TRAF3 is required for IFN-β production in response to RNA virus, and TRAF3−/− cells severely impaired the production of IFN-β in response to virus infection in human cells." (PMID 29599773, 2018). "RBM14 has also been found to interact with TRAF3 in immunocomplexes that arise in response to dsDNA and dsRNA sensors, further suggesting a role in the innate immune response to viral infection." (PMID 30429226, 2018). "The MAVS-TRAF3 complex formation is crucial for IFN response to RNA viruses, and in the early phase of viral infection, TRAF3 acts as a linker in the assembly of the active MAVS-TRAF3-TBK1 signaling complex that also includes NEMO." (PMID 29599773, 2018). "Here, our findings uncover the phenomenon of MAVS/TRAF3/TRAF6 downregulation at the early stage of viral infection, and partially clarify the mechanisms of the dynamics of downregulation of the signalosome and IFNs induction." (PMID 29734366, 2018). "The deubiquitinases OTUB1/2, UCHL1, MYSM1 and DUBA inhibit K63-linked ubiquitination of TRAF3 or TRAF6 and negatively regulate IFNs production during viral infection." (PMID 29734366, 2018). "Except for K63-linked polyubiquitination, TRAF3 also undergoes K48-linked ubiquitination by the ubiquitin ligase Triad3A during virus infection, which results in proteasomal degradation of TRAF3 and termination of the type I IFN response." (PMID 27026194, 2016). "Upon stimulation with ligands or viral infection,TRAF3 appears on membrane-bound fragments originating from Golgi." (PMID 27094905, 2016).
viral infection (continued). "So far, several deubiquitinases such as DUBA, OTUB1/2, UCHL1, and OTUD7B have been reported to cleave TRAF3 ubiquitin chains in response to viral infection." (PMID 24763515, 2014). "Since multiple E3 ligases have been proposed to conjugate ubiquitin onto TBK1 during virus infection including TRAF3, Mind bomb and Nrdp1, it is possible that RNF11 (and the A20 complex) also blocks TBK1/IKKi interactions with Mind bomb and Nrdp1." (PMID 23308279, 2013). "In contrast, retention of TRAF3 at the ER-to-Golgi vesicular transport system blunted the ability of TRAF3 to interact with MAVS upon viral infection and consequently decreased type I IFN response." (PMID 22792062, 2012). "Virus infection or exposure to double-stranded RNA has also been documented to decrease TRAF3 levels in a dose-dependent manner." (PMID 22709905, 2012). "Following viral infection, the ERGIC reorganizes into small punctate structures allowing TRAF3 to associate with Mitochondrial AntiViral Signaling (MAVS), an essential adaptor of the anti-viral type I IFN response." (PMID 22792062, 2012). "TRAF3 is a critical signalling molecule for IFNβ activation in response to virus infection, and is a well established binding partner for the TBK1 adaptor protein TANK, residing in a trimeric complex containing TBK1." (PMID 20174559, 2010). "TRAF3 appears to undergo a biphasic ubiquitination following virus infection that is crucial for regulation of RIG-I dependent signaling to the antiviral response." (PMID 19893624, 2009). "The present results suggest a biphasic regulation or “immune-editing”, whereby TRAF3 is Lys63 polyubiquitinated early after virus infection to bridge protein-protein interactions between MAVS and TBK1/IKKε." (PMID 19893624, 2009). "TRAF3 appears to undergo sequential ubiquitin “immuno-editing” following virus infection that is crucial for regulation of RIG-I-dependent signaling to the antiviral response." (PMID 19893624, 2009). "In recent years, the functions and regulatory mechanisms of TRAF3 in its dependent signaling pathways have been thoroughly elucidated, providing a new target for the clinical prevention and treatment of some tumors, viral infections, and other diseases." (PMID 36845015, 2023). "Indeed, virus infection causes interaction between USP25 and TRAF3 (or TRAF6), leading to the stabilization of TRAF3 (or TRAF6) and thus allowing for the production of type I IFNs as well as proinflammatory cytokines." (PMID 35008917, 2022). "The effects of the knockdown and overexpression of TRAF3 on virus infection were evaluated." (PMID 35573779, 2022). "More importantly, maintaining the stable expression level of TRAF3 may contribute to its regulatory role in the innate immune system in defending against virus infection." (PMID 35573779, 2022). "Viral infection leads to TRAF3 re-localization from the cytoplasm to mitochondria." (PMID 34745083, 2021). "Additionally, the TRAF3 substrate TBK1 was also recruited to TFG upon viral infection or stimulation with Poly(I:C)." (PMID 33411856, 2021). "However, our LC-MS/MS analysis did not detect any peptide derived from MAVS, a mitochondrial protein that is known to bind to TRAF3 upon viral infection." (PMID 34745083, 2021). "In addition to these studies, we previously showed that the ER-to-Golgi vesicular transport system serves as an organizing membrane-rich platform allowing the proper positioning of TRAF3 with MAVS onto the mitochondria network following virus infection." (PMID 33411856, 2021). "Therefore, we also performed co-immunoprecipitation of the endogenous proteins to further characterize the dynamics of interaction between TFG and TRAF3 upon viral infection." (PMID 33411856, 2021). "β-arrestin 2 did not associate with TBK1 or TRAF3 without virus infection, while the situation changed after infection." (PMID 33243993, 2020).